PPARG (peroxisome proliferator activated receptor gamma)
Diseases named in the same sentence as PPARG in open-access papers (continued):
Sharing a sentence is not in itself a finding about the gene and the disease.
breast cancer (continued). "In this context, we identified palmitate-induced lipotoxicity as a main effect of PPARγ inhibition in ERBB2-positive breast cancer cells." (PMID 19298655, 2009). "Our findings indicate that PPARγ activity enables ERBB2-positive breast cancer cells, which produce high levels of fat, to convert fatty acids to triglycerides, allowing these cells to avert the cell death that results from lipotoxicity." (PMID 19298655, 2009). "Recently, a new approach using activators of peroxisome proliferator-activated receptor gamma (PPARγ) to inhibit proliferation and increase cell death in breast cancer cell lines has given hope to the development of a new class of anticancer drugs." (PMID 19958503, 2009). "ERBB2-positive breast cancer cells are more sensitive to inhibition of PPARγ activity by the antagonist GW9662." (PMID 19298655, 2009). "PPARγ inhibition in ERBB2-positive breast cancer cells resulted in cell death and apoptosis, similar to the effects of PBP and NR1D1 inhibition (Kourtidis A, Carkner RD, Eifert C, Brosnan MJ, Conklin DS; unpublished data)." (PMID 19298655, 2009). "PPARγ activity is necessary for the viability specifically of ERBB2-positive breast cancer cells, in a similar manner to PBP and NR1D1 (Kourtidis A, unpublished data; Carkner RD, Eifert C, Brosnan MJ, Conklin DS)." (PMID 19298655, 2009). "In our study, the PPARγ agonist rosiglitazone activated PPARγ and inhibited progression of breast cancer." (PMID 19356226, 2009). "In this study, we have begun to elucidate the functional significance of endogenous PPARγ activation in breast cancer using an in vitro model." (PMID 19061500, 2008). "Peroxisome proliferator-activated receptor gamma (PPARγ), a member of the nuclear-hormone receptor family, has shown potential as a therapeutic target for prevention and treatment of breast cancer." (PMID 19061500, 2008). "In accordance with a bidirectional interaction, Wang and colleagues demonstrated that ERs are capable of inhibiting ligand-induced PPARγ activation in two different breast cancer cell lines." (PMID 18584035, 2008). "Peroxisome proliferator-activated receptor gamma (PPARγ) is a member of the nuclear hormone receptor superfamily and is highly expressed in many human tumors including breast cancer." (PMID 19061500, 2008). "In breast cancer cells, the PPARγ antagonist GW9662 inhibited growth and also surprisinglyenhanced rosiglitazone-induced growth inhibition." (PMID 18615184, 2008). "The findings on breast cancer support the broad anticancer activities of PPARγ signaling, and also reflect the studiesin colon cancer." (PMID 18528521, 2008). "By immunohistochemical analysis, PPARγ expression has been detected in 42% (99/238)to 58% (101/170) of human breast cancer samples, correlating positively with ERexpression and improved clinical outcome." (PMID 19125177, 2008). "Compared to adipocytes, breast cancer cells exhibit low PPARγ expression and activity reflected by a less than 2-fold induction of PPRE-activity after ligand stimulation." (PMID 18584035, 2008). "The PPARγ agonist GW7845 delays the developmentof mammary tumors in immunocompetent mice treated with medroxyprogesteroneacetate followed by DMBA administration by an average of 2 months." (PMID 18645617, 2008). "MK866 blocks the 5-lipoxygenase pathway of arachidonic acidmetabolism, increases the expression of PPARα and PPARγ in breast cancer cells, and induces apoptosis.As well, in lung cancer cells, MK886 increased PPARγ reporter activity." (PMID 18615184, 2008). "PPARγ has been identified as a potential target for breast cancer therapy based on the fact that its activation by synthetic ligands affects the differentiation, proliferation, and apoptosis of cancer cells." (PMID 19061500, 2008). "These mice that expressed both activated PPARγ and PyV-MT showed accelerateddevelopment of mammary tumors." (PMID 18584037, 2008).
breast cancer (continued). "In this review, we attempt to summarize the possible influence of chemical PPAR ligands on the molecular pathways involved in the initiation and progression of breast carcinoma, with a major emphasis on PPARγ agonists thiazolidinediones (TZDs)." (PMID 18645617, 2008). "Cytoplasmic PPARγ was also detected in the cytoplasm(58%) of infiltrating breast carcinoma samples and was proposed as anindependent prognostic factor for patients with ductal carcinoma." (PMID 18596912, 2008). "In breast cancer, the PPARγ antagonist GW9662 has recently been used to definitively exclude PPARγ activation in apoptotic and proliferative responses to selected PPARγ agonists." (PMID 16519808, 2006). "The ligands for PPARγ have been shown to increase the expression of BRCA 1 protein in human breast cancer cells, indicating that PPARγ plays a crucial role in BRCA1 regulatory pathways involved in the pathogenesis of breast and sporadic ovarian cancer." (PMID 15583697, 2005). "In combination with PPARγ agonists, retinoids have been reported to enhance growth inhibition and cell death in human breast cancer cell lines in vitro, possibly via interactive heterodimerisation of retinoid receptors and PPARγ." (PMID 15505623, 2004). "For example, 15d-PGJ2 has been shown to have potent PPARγ-independent proapoptotic effects on breast cancer cells, which exhibit constitutive Stat3 activation linked to cooperative activity of Src and JAK family tyrosine kinases." (PMID 15316561, 2004). "Independent studies have shown that induction of COX-2 and inactivation of PPARγ occurred during the development and progression of human breast carcinoma." (PMID 15266333, 2004). "Breast carcinoma cells treated with PPARγ agonist show dramatic morphological changes, and express E-cadherin and b-casein, markers of breast cell differentiation." (PMID 15266333, 2004). "Peroxisome proliferator-activated receptor (PPAR) γ is expressed in human colon cancer, prostate cancer and breast cancer cells, and PPARγ activation induces growth inhibition in these cells." (PMID 11044367, 2000). "This makes postmenopausal women particularly susceptible to cancer thriving on lipid metabolism, and developing a further understanding of how PPARγ's activity is influenced by menopausal status can provide insight into developing targeted therapies for breast cancer prognosis across tumor subtypes." (PMID 41236441, 2025). "To test whether activation of the PAM signaling pathway is responsible for resistance in HER2-positive breast cancer induced by PPARG, we introduced Everolimus, an mTOR inhibitor widely used in studies of PAM signaling pathway inhibition." (PMID 40303293, 2025). "Similarly, the conjugates of ω-3 PUFAs with ethanolamine induced autophagy in MCF-7 breast cancer cells through activation of PPARγ." (PMID 39863855, 2025). "Given the potential of PPARγ regulators in overcoming radioresistance and chemoresistance in cancer therapies, we hypothesized that KA may enhance the efficacy of breast cancer radiotherapy." (PMID 39770941, 2024). "Conversely, the relationship between PPARγ and Nur77 has antagonistic effects on breast cancer." (PMID 38933330, 2024). "Our previous work demonstrated a novel approach to overcoming cancer cell plasticity by converting invasive breast cancer cells into post-mitotic functional adipocytes through the combined use of a PPARγ agonist (Rosiglitazone) and a MEK inhibitor (Trametinib)." (PMID 39273076, 2024). "In ER-resistant breast cancer, anti-PPARG therapy can promote cell apoptosis." (PMID 38516703, 2024). "The dual targeting on VEGFR2 and PPARγ is an effective strategy for breast cancer therapy." (PMID 37942548, 2024). "Interestingly, the results of our study confirm our former investigation into the subcellular localization of PPARγ and RXRα and its influence on survival in breast cancer patients." (PMID 37509273, 2023). "In this regard, PPARγ antagonists impair cell proliferation and mammary tumor growth." (PMID 36670988, 2023).
breast cancer (continued). "Moreover, perturbation of PPARγ signaling with novel PPARγ agonists and antagonists is gaining attention as a strategy for the treatment of several cancers, including breast cancer." (PMID 37649895, 2023). "Furthermore, PPAR modulates the lipid homeostasis in liver and the blockage of PPARγ can suppress breast cancer progression." (PMID 37633919, 2023). "Variations in TNFα, PPARγ, and IRS-1 genes are associated with survival in breast cancer patients." (PMID 37886170, 2023). "Similarly, in breast cancer, the deletion of specific PPARγ in CAA downregulates BRCA1 expression and accelerates tumor formation and progression." (PMID 37251321, 2023). "Therefore, we considered IGF1, LEP, ADIPOQ, NR3C1, and PPARG as potential predictors for the poor prognosis of patients with breast cancer." (PMID 35317079, 2022). "PPARγ antagonist treatment reduced melanoma or breast cancer brain metastasis burden in animals." (PMID 35954274, 2022). "In this study we describe TRIB3 as a regulator of PPARγ expression in breast cancer cells, and we hypothesize that TRIB3 achieves this through binding to the WRAD complex and regulating the H3K4me3 mark around the PPARγ locus." (PMID 36142452, 2022). "This molecular mechanism for promoting breast cancer development might also be attributed to the promotion of PPARγ on the Wnt signaling pathway." (PMID 36611922, 2022). "Notably, the phosphorylation of PPARγ at Serine 112 was found to be predominant in immunologically cold tumors, indicating its involvement in an immune surveillance evasion mechanism in breast cancer." (PMID 36139700, 2022). "PPARγ mediated apoptosis induction by n-3 polyunsaturated fatty acids (n-3 PUFA) in a breast cancer cell line, which might explain the beneficial effects of diets enriched in n-3 PUFA." (PMID 35954274, 2022). "High glucose activated PPARα and PPARγ expression in breast cancer cell cultures." (PMID 35954274, 2022). "Therefore, it is necessary to either synthesize new PPARγ activators with clinical value and few toxic side effects or find other drugs that can be used in combination with existing ligands for breast cancer treatment." (PMID 36611922, 2022). "However, a recent study revealed that activated PPARγ promotes tumor vascularization and growth in breast cancer." (PMID 35954274, 2022). "In 1999, it was first discovered that GW7845 (an L-tyrosine derivative) could be used as PPARγ activator to prevent the progression of experimental breast cancer in rats." (PMID 36611922, 2022). "A recent study indicated that poly lactic-co-glycolic acid (PLGA) nanoparticle of cinnamic acid at concentration of ≥25 μM inhibited MCF-7 cellular proliferation via PPARγ signaling pathway, leading to a drop of metabolic activity and Ki-67 antigen to exert its cytotoxic effects on breast cancer." (PMID 36092543, 2022). "In this study, we show that TRIB3 is able to regulate PPARγ expression in breast cancer cells." (PMID 36142452, 2022). "Similarly, in a breast cancer model, PPARγ was found to induce M2 polarization through the induction of integrin β3." (PMID 35954274, 2022). "Therefore, blocking the interaction between PPARγ and Nur77 can be used as a clinical approach for PPARγ ligand-independent treatment of breast cancer." (PMID 36611922, 2022). "However, the mechanism of RGZ in breast cancer angiogenesis that targets PPARγ, HIF, TLR4, and AMPK signaling pathways needs to be clarified." (PMID 36114448, 2022). "PPARγ expression has been shown to be upregulated in certain breast cancer patients." (PMID 36142452, 2022). "The activation of PPARG has been increasingly shown to inhibit the proliferation, migration and invasion of breast cancer cells, while its down-regulation promotes the progression of cachexia in breast cancer patients." (PMID 36425653, 2022). "Moreover, inhibition of PPARγ signaling by its antagonist inhibits breast cancer stem cells in the HER2+ subtype." (PMID 36114448, 2022).
breast cancer (continued). "However, when breast cancer cells were co-injected with PPARγ-overexpressing fibroblasts, tumor growth was significantly increased." (PMID 35954274, 2022). "PKM2 is inhibited by PPARγ in two breast cancer cell lines, and this inhibition might decrease ATP levels and avoid apoptosis." (PMID 34168538, 2021). "However, most of the existing studies on PPARG in breast cancer are one-sided, focusing only on a single research field." (PMID 34567087, 2021). "PPARγ expression is a positive prognostic factor in luminal and ductal breast cancer." (PMID 34631530, 2021). "Petersen found that PPARγ activity may be an important determinant of alcohol-related breast cancer." (PMID 34066125, 2021). "Thus, activation of PPARγ serves as a key factor in the proliferation and invasion of breast cancer cells and it is a potential therapeutic target for breast cancer." (PMID 34199169, 2021). "Supporting this notion, concomitant treatment with HDAC inhibitors was required to license the tumor-suppressive effects of PPARγ agonists in triple-negative and endocrine-refractory breast cancer cells, and combination therapy also restrained angiogenesis in a tube formation assay." (PMID 34580286, 2021). "Additionally, it was reported that pioglitazone, one of PPARγ agonists, inhibited breast cancer growth by regulating JAK2/STAT signaling pathway in vitro and in vivo." (PMID 33917914, 2021). "Previous studies found that PPARγ activation could induce the differentiation of cancer stem cells to mature cancer cells, promoting the proliferation capability of breast cancer." (PMID 35186942, 2021). "Thus, PPARG signaling is crucial for breast cancer-derived factors altering lipid accumulation and mitochondrial functions." (PMID 34490085, 2021). "In contrast, the interaction between PPARγ and Nur77 plays an antagonistic role in breast cancer." (PMID 34775964, 2021). "Moreover, we compared the PPARG protein expression in human normal breast cell line (Hs 578Bst) and in breast cancer cell lines MCF7, UACC812, and SK-BR-3 cells to confirm the lower expressions of PPARG." (PMID 34567087, 2021). "An immunohistochemistry study conducted on 170 infiltrative breast carcinomas revealed that PPARγ was inversely correlated with histological grade, indicating a favorable impact of PPARγ expression on disease-free survival of patients with ductal breast carcinoma." (PMID 33808259, 2021). "Thus, PPARγ activation is beneficial for controlling breast cancer, suggesting a useful role for these molecules in the treatment of breast carcinoma." (PMID 32224850, 2020). "Besides the activation of the autophagic flux, ligand-activated PPARγ exerts also pro-apoptotic effects in breast cancer cells, thus inducing cell growth suppression." (PMID 33352766, 2020). "In addition, Peroxisome proliferator-activated receptor gamma (PPARγ) was overexpressed in BRCA1-defective breast cancer patients, and in vascular smooth muscle cells PPARγ was found to regulate PFKP." (PMID 32470015, 2020). "Till date, another clinical trial using synthetic PPARγ agonist rosiglitazone has been reported in the ClinicalTrials.gov databases, whereas 40 clinical studies have been conducted with dietary ω-3 PUFAs in breast cancer." (PMID 32937951, 2020). "This review could allow a better comprehension of the PPARγ agonists as potential pharmacological or nutritional compounds against breast cancer." (PMID 32937951, 2020). "Interestingly, PPARγ is also expressed in different types of tumors, including colon, prostate, and breast cancer." (PMID 32937951, 2020). "Despite limited in perspective, the overall suggestions from accumulated data relating to PPARγ and breast cancer strongly highlight that this receptor may have an important role as tumor suppressor." (PMID 32937951, 2020).
breast cancer (continued). "In summary, our findings demonstrate that TAZ is specifically up-regulated by FFAs/PPARγ in adipocytes upon dietary fat stimulation and facilitates breast cancer proliferation and stemness, implying a potential role of adipocytic TAZ in the pathogenesis of breast cancer." (PMID 33318171, 2020). "Interestingly, activation of PPARγ by its natural and synthetic agonists has been found to modulate the expression of several genes associated with tumorigenesis, further highlighting that this nuclear receptor could represent a new promising target for the treatment of breast cancer." (PMID 32937951, 2020). "If true, our finding that PPARγ expression was reduced in the HFD offspring and reversed by maternal grape juice intake suggests that PPARγ may protect against mammary cancer." (PMID 32731460, 2020). "Moreover, Rovito and coworkers have described that different conjugates of ω-3 PUFAs induce autophagy in breast cancer cells through PPARγ activation." (PMID 32937951, 2020). "Moreover, it has been reported that ligand-activated PPARγ can also reduce tumor growth counteracting the leptin-signaling, which is well-known to sustain breast cancer progression." (PMID 33352766, 2020). "Zhou and coworkers found that troglitazone and rosiglitazone stimulate autophagy in triple-negative MDA-MB-231 breast cancer cells in a PPARγ-dependent manner through the upregulation of the hypoxia-inducible factor 1 (HIF1α), which is required for the hypoxia-induced autophagy." (PMID 32937951, 2020). "Besides, AR and PPARγ are still complicated targets for breast cancer treatment because studies gave contradictory conclusions." (PMID 33246450, 2020). "In addition, it has been reported that ligand-activated PPARγ regulates several signaling pathways involved in tumorigenesis as well as other molecular mechanisms to inhibit breast cancer proliferation." (PMID 33352766, 2020). "Indeed, PPARγ activation in the epithelial breast cancer cells results in a reduced cell growth and motility as well as an increased autophagy and apoptosis." (PMID 33352766, 2020). "Indeed, ligand-activated PPARγ induces breast cancer cell differentiation into a less malignant phenotype, enhancing the expression of markers of normal breast development." (PMID 33352766, 2020). "Moreover, the ω-3 PUFA docosahexaenoic acid (DHA) acting as an agonist of PPARγ stimulates apoptosis in breast cancer cells increasing the expression of the tumor suppressor syndecan-1 (SDC-1)." (PMID 33352766, 2020). "Here, our study establishes the FFA/PPARγ/TAZ/Resistin axis as an essential signaling pathway in adipocytes that facilitates breast cancer proliferation and stemness, with an implication of a diagnostic and therapeutic avenue for breast cancer." (PMID 33318171, 2020). "Accordingly, we also found that FFA-pretreated–Adipo-CM enhanced mammosphere formation ability, while T0070907-inhibited FFA-pretreated–Adipo-CM induced mammosphere formation, indicating the involvement of FFA–adipocytic PPARγ in the regulation of breast cancer cell stemness." (PMID 33318171, 2020). "The aim of this study was to investigate the expression of the nuclear receptor PPARγ, together with that of the cyclooxygenases Cox-1 and Cox-2, in breast cancer (BC) tissues and to correlate the data with several clinicobiological parameters including patient survival." (PMID 32085795, 2020). "The rationale is that there could be an altered PPARγ modulation, in line with literature reports indicating an alteration in PPARγ expression in breast cancer cells." (PMID 31511776, 2019). "In addition, PPARγ, as a nucleus transcription factor, was found to negatively regulate cell proliferation, in which upregulation of PPARγ significantly decreased proliferation in human breast cancer cells or colon cancer cells." (PMID 31428652, 2019). "Moreover, we observed that LATS2 is required for induction of luminal breast cancer cell death by the PPARγ agonist RGZ." (PMID 30456386, 2018).